CD63 (CD63 molecule)
Diseases named in the same sentence as CD63 in open-access papers (continued):
Sharing a sentence is not in itself a finding about the gene and the disease.
melanoma (continued). "Therefore, we compared the detection and quantification of CD63+ exosomes from unfractioned samples (cell culture supernatants from human macrophages and melanoma cells, and human plasma) and exosomes purified from the same samples." (PMID 19381331, 2009). "Interestingly, paired T-test showed that plasma levels of Cav1+ exosomes were significantly higher than levels of CD63+ exosomes in melanoma patients (P = 0.004)." (PMID 19381331, 2009). "However, plasma exosomes concentration was significantly higher in melanoma patients with respect to healthy individuals (P<0.001 for both CD63+ and Cav1+ exosomes)." (PMID 19381331, 2009). "Thus, CD63 appears capable of regulating melanoma cell functions, although the mechanism of this regulation is unclear." (PMID 16318634, 2005). "The current study demonstrates that CD63 is capable of transducing signals in melanoma cells that requires extracellular Ca2+ and is inhibited by the protein kinase C inhibitor chelerythrine, and that CD63 is associated with serine protein kinase activity in melanoma cells." (PMID 16318634, 2005). "This associated protein kinase activity may play a role in the mechanism whereby CD63 exerts its previously reported effects on melanoma cell function." (PMID 16318634, 2005). "At coating concentrations of 1 ug/ml, each of the CD63 mAbs promoted melanoma cell adhesion." (PMID 16318634, 2005). "The tetraspan protein CD63, originally described as a stage-specific melanoma antigen but also present in a number of normal cells, regulates melanoma cell growth in nude mice, motility in serum containing media, and adhesion to several extracellular matrix proteins." (PMID 16318634, 2005). "CD63 was capable of transmitting a signal in melanoma cells that required extracellular calcium." (PMID 16318634, 2005). "Thus, the interaction of melanoma cells expressing CD63 to immobilized CD63 mAbs resulted in the generation of a transient signal that required extracellular calcium to effect melanoma cell adhesion." (PMID 16318634, 2005). "In addition, this study demonstrates that CD63 is capable of transducing signals in melanoma cells that requires extracellular Ca2+ and is inhibited by the protein kinase C inhibitor chelerythrine." (PMID 16318634, 2005). "We found that miR-195-5p overexpression in BRAF-mutated melanoma cells causes an increase in the expression levels of some EVs biogenesis-related genes like RAB27b, RAB31, and/or FLOT2, which was accompanied by a consequent increase in CD63 and CD9 positive EVs secretion." (PMID 37174717, 2023). "Finally, Cd63 localizes to early melanosomes, highly specialized organelles that originate from LE-type precursors, and was shown to be required for melanogenesis in human melanoma cells." (PMID 33274330, 2020). "In addition, we reported, for the first time, the assembly of a supramolecular complex containing Timp1, CD63, and β1-integrins at the cell surface in melanoma cells, and its involvement in the acquisition of an anoikis-resistant phenotype through the PI3K signaling pathway." (PMID 28430130, 2017). "Therefore, it is possible to suggest that, in this model, the tight complex comprised by Timp1, CD63 and β1-integrins contributes to the acquisition of malignant phenotype, since the interaction among these three molecules was observed only in melanoma cell lines." (PMID 23522389, 2013). "In addition, our data point TIMP1, mainly together with CD63, as a potential biomarker of melanoma." (PMID 23522389, 2013). "The analysis of membrane-enriched extracts immunoprecipitated with anti-CD63 antibody followed by Western blot using anti-β1-integrin antibody showed that β1-integrin-CD63 interaction occurs in all lineages, but is more intense along melanoma progression (4C, 4C11- and 4C11+ cell lines)." (PMID 23522389, 2013).
melanoma (continued). "Melanoma cells specifically adhered to immobilized CD63 mAb, and the adhesion was inhibited by chelerythrine but not by genistein, suggesting that signaling pathways involving protein kinase C activity, but not genistein-sensitive tyrosine kinases, play a role in the stimulation by CD63." (PMID 16318634, 2005). "A number of studies have suggested that CD63 may regulate melanoma cell functions." (PMID 16318634, 2005). "In this case, melanoma (tumor) cells can be distinguished by SOX10, S100B, and CD63 protein abundance." (PMID 41333415, 2025). "Of note, to better explore LEVs markers, we demonstrate tetraspanin labelling (CD9, CD63 and CD81) in our LEVs isolates from pooled plasma samples from nevi and melanoma patients." (PMID 41268555, 2025). "Of the three tetraspanins (CD9, CD63, and CD81) we have studied in the context of melanoma, only CD81 affects patient survival." (PMID 40521809, 2025). "TIMP1, through its interaction with beta-1 and CD63, activates the PI3K-AKT pathway, thereby mediating anoikis resistance in melanoma and facilitating tumor progression in ccRCC14,47." (PMID 38802480, 2024). "As observed in melanoma-bearing mice, EO771 and 4T1-GFP tumor-bearing mice receiving reserpine treatment also exhibited less CD63, and therefore less TEVs, in their plasma." (PMID 38405101, 2024). "In summary, they suggested that CD81+CD63+EVs contribute to restricting metastasis development in breast and melanoma in lung tissue and that tumors with low levels of CD81+CD63+EVs have a high tendency to develop lung metastasis." (PMID 39091989, 2024). "The modulation of the CD63 and TSG101 content in sEVs of melanoma cells, as observed by us, was also described as important in promoting the more or less pro-invasive character of secretory vesicles." (PMID 39596498, 2024). "In the A2058 spheroids, CRP PEVs significantly increased CD81- and decreased CD9-containing melanoma EV formation, whereas FFV PEVs increased the formation of CD63- and CD81-containing melanoma EVs." (PMID 39695652, 2024). "In the presence of TIMP-1, CD63 can interact with integrin β1, forming a TIMP-1/CD63/integrin β1 complex, which leads to malignant progression, as in the case of melanoma genesis." (PMID 37443843, 2023). "EVs derived from a melanoma cell line were characterised following MISEV2018 guidelines and incubated with anti-CD63-coated beads for flow cytometry analysis." (PMID 35135541, 2022). "Other tetraspanin proteins including CD63, CD73, CD151, and Tspan8 have also been shown to modulate the EMT process and tumor progression in colorectal cancer, gastric cancer, melanoma, and renal cell carcinoma." (PMID 35280793, 2022). "The most recent study demonstrated that Vemurafenib-resistant melanoma cells (Mel28 and A375 cell lines) also form the TIMP1/CD63/β1-integrin supramolecular complex." (PMID 34502227, 2021). "Mel1 exosomes were positive for CD9, CD63 and Alix exosomal markers, and also for CD271 melanoma CSC marker." (PMID 33052601, 2021). "Both CD63 and CD9 play a role in melanoma progression and metastasis, although most classical reports were based on tetraspanin overexpression." (PMID 34012515, 2021). "As for previous experiment, serial dilutions were coupled to beads and stained with anti-CD63 and anti-CD59 for melanoma-EVs or anti-CD63 and anti-MHC-I for T-lymphoblasts-EVs." (PMID 28900146, 2017). "In a first approach, we investigated, by confocal microscopy the localization of CD63+ intracellular vesicles in fixed and permeabilized CTL/melanoma cell conjugates." (PMID 26940455, 2016). "Peptide-pulsed melanoma cells engaged in cognate interactions with CTL, displayed a significant enrichment of CD63 towards the lytic synapse." (PMID 26940455, 2016). "In these analyses, we were able to confirm expression of transcripts specific for CD63, ErbB3, CD44, and IGF-1-R in melanoma cells and melanoma cell lines in all samples tested." (PMID 24489649, 2014).
melanoma (continued). "Patient-derived melanoma cells were defined as CD45−/CD31− cells co-expressing CD146 and/or CD166 and/or CD63." (PMID 24489649, 2014). "In human melanoma cell lines, in which TIMP1 and beta-1 integrin were also found to be interacting, TIMP1 and CD63 levels together was shown to correlate significantly with colony formation capacity." (PMID 23522389, 2013). "Human melanoma cell adhesion to three different immobilized CD63 mAbs was almost totally inhibited by EGTA, indicating that external Ca2+ plays an important role in human melanoma cell adhesion to the mAbs (top)." (PMID 16318634, 2005). "CD63 has been suggested as a resistance mediator by tumour-derived exosomes containing doxorubicin and other cytotoxic agents in MCF7 cell lines and mediates anoikis resistance in murine melanoma cell lines." (PMID 38391955, 2024). "Additionally, TIMP1, integrating with CD63 and β1‐integrins as a complex, confers anoikis resistance by activating PI3K signaling pathway in melanoma." (PMID 36507553, 2023). "For instance, benign granular cell tumors are positive for S-100 protein, CD63, CD68 and neuron-specific enolase whereas atypical fibroxanthoma stains negatively for S100 protein, Melan-A, human melanoma black (HMB)-45 pan-cytokeratin (CK) and actin and positively for CD68 and vimentin." (PMID 36832159, 2023). "Western blot analysis shows enrichment for CD63 and Alix in the iEV fraction, but not in melanoma cell lysates." (PMID 35628321, 2022). "Melanoma EVs were still detected on supernatants after several rounds of capture using anti-CD63-coated beads, suggesting that not all the EVs carrying the epitope were captured in a single step." (PMID 35135541, 2022). "The human melanoma cell line FEMX‐I has been used to identify the VOR complex, and the morphology of EVs derived from it has already been documented by CD63‐immunoelectron microscopy." (PMID 34429859, 2021). "Therefore, we decided to make repeated treatments to melanoma cells during a 7d period with peptides of CD9, a scrambled control or CD63 as a specificity control." (PMID 34012515, 2021). "By analyzing the dominant ligand-receptor pairs contributing to this spatial organization, we identified that the interactions between CD63 and TIMP1 contributed ~66% to the cellular interaction potential of melanoma malignant cells while HNC cells expressed CD63 and TIMP1 at much lower levels." (PMID 32541867, 2020). "Supporting this notion, Cd63 is considered a negative driver of advanced stages of melanoma, as it inhibits epithelial-mesenchymal transition (EMT), and thus invasive migratory behavior." (PMID 33274330, 2020). "Finally, silencing CD63 reduced the levels of β-catenin protein and its downstream target MMP-2 inhibiting metastatic lung colonization of ovarian and melanoma tumors." (PMID 29946318, 2018). "CD63 is a suppressor of melanoma tumor progression and has been shown to be a negative driver of mesenchymal transition." (PMID 28400597, 2017). "Among the proteins that were found in MVs as well as both exosome subpopulations isolated from melanoma cells, we found suggested EV and exosome marker proteins ALIX, TSG101, CD9, CD81 and CD63, however their relative abundance was higher in LD-Exo and HD-Exo as compared to MVs." (PMID 26931825, 2016). "In the present study, melanoma cells were defined as CD45-negative and CD31-negative cells (excluding leukocytes and endothelial cells) that co-expressed at least one of the classical melanoma-related antigens, namely CD146, CD166 or CD63." (PMID 24489649, 2014). "For instance, it has been reported that CD63 is strongly expressed on the cell surface during the early stage of malignant melanoma, but this localization is weaker or absent in the malignant stages of melanoma compared to normal melanocytes." (PMID 24884960, 2014).
melanoma (continued). "Higher level of CD63 protein expression was observed in pre-malignant 4C melanocytes and non-metastatic 4C11- melanoma cells compared to non-tumorigenic melan-a melanocytes and metastatic 4C11+ melanoma cells." (PMID 23522389, 2013). "In our study, the presence of CD63 protein was observed in all cell lines, especially in non-metastatic 4C11- melanoma cells." (PMID 23522389, 2013). "The interaction between CD63 and Timp1 was observed in pre-malignant 4C melanocytes and 4C11- and 4C11+ melanoma cell lines, but not in the parental melan-a melanocytes." (PMID 23522389, 2013). "A similar observation was made for CD63 after rabip4s knock-down in the SKMel28 melanoma cell line (not shown)." (PMID 23144738, 2012). "Transfection of the CD63 negative melanoma cell line KM3 with genomic CD63 resulted in cells with similar in vitro growth rates as control cells, but much slower growth rates in vivo when cells were injected intradermally in nude mice." (PMID 16318634, 2005). "Also, we identified that melanoma-derived LEVs may be more enriched with CD9, CD63 and CD81 than nevi-derived EVs." (PMID 41268555, 2025). "The detection of GFP+/Rh+ and CD63+/GFP+ events in A375 melanoma cells expressing GFP-SR-B1, but not CD81+/GFP+ events, suggests that GFP modification of SR-B1 may prevent GFP-SR-B1 sorting to CD81+ exosomes." (PMID 26964503, 2016). "Once it was shown that in human breast epithelial cells the interaction among CD63, TIMP1 and β1-integrin can regulate apoptosis, we analyzed the possible differential interaction among CD63, Timp1 and β1-integrin in cell lines corresponding to different stages of melanoma progression." (PMID 23522389, 2013). "In order to confirm that the cell adhesion to immobilized AHN-16 was due to reactivity with the CD63 epitope, Fab fragments of AHN-16 and normal mouse IgG were prepared as described in the Materials and Methods, and tested for their ability to inhibit melanoma cell adhesion to immobilized AHN-16." (PMID 16318634, 2005). "CD63 is not expressed in normal melanocytes, but is expressed in nevi and many melanoma cells." (PMID 16318634, 2005). "Furthermore, metastatic 4C11+ melanoma cells present decreased CD63 expression compared to non-metastatic 4C11-melanoma cells, corroborating the data showing that inhibition of CD63 expression increased cell motility, matrix degrading activity and invasiveness of melanoma cells in vitro." (PMID 23522389, 2013). "Using this approach, even melanoma populations that expressed only low amounts of CD146 or CD166, or were largely negative for CD63, were included in our studies." (PMID 24489649, 2014). "In mouse melanoma B16F10 cells, this compound had multiple effects, including the upregulation of TYR and CD63 mRNA(s) and protein(s), without affecting the levels of the melanogenic master transcriptional regulator microphthalmia transcription factor (MITF) or TYRP-1 mRNA(s)." (PMID 35011407, 2021).
COVID-19 (37 papers, 2020 to 2025). A disease caused by infection with severe acute respiratory syndrome coronavirus 2. "Platelet activation was obvious in individuals with severe COVID-19, as measured by surface expression of P-selectin and CD63, and it was substantially linked with D-dimer levels." (PMID 38715614, 2024). "Specifically, clusters associated with COVID-19 had higher expression of markers important for the activation and recruitment of basophils, including CD11b, CD63, and CXCR4." (PMID 34548411, 2021). "Notably, overexpression of the CD9 and CD63 shows the involvement of extracellular vesicles in COVID-19 pathogenesis and can be associated with the faster virus spreading, mediating communication between infected and virus free cells." (PMID 36230912, 2022). "ALIX and CD63, internal and external EV markers respectively, were present in the evaluated fractions of the control and COVID-19 samples." (PMID 39382598, 2025). "Patients with severe COVID-19 have higher gene and protein expression of CD63, with this expression coinciding with neutrophil degranulation." (PMID 39253969, 2024). "Incubation of plasma from patients with severe COVID-19 with platelets from healthy volunteers increased the level of platelet activation markers (P-selectin and CD63)." (PMID 39036222, 2024). "Both CD9 and CD63 are involved in exosome formation, and COVID-19 plasma exosomes stimulate pro-inflammatory responses that affect CD4/CD8 T cells, and CD14+ monocytes." (PMID 39712003, 2024). "Consistently, platelet activation is evident by increased expression of P-selectin CD40 and CD63 on the surface of platelets from patients with COVID-19." (PMID 38715614, 2024). "Corroborating with these data, we also observed an increase in mRNA expression of CD63 in whole blood and leukocytes of severe COVID-19 patients." (PMID 38262689, 2024). "The distribution of neutrophils across disease states was consistent with the results of bulk mRNA-seq data on immune infiltration, with Neutrophil CD63+ and Neutrophil S100+ being increased in COVID-19 severe compared to healthy controls." (PMID 38674681, 2024). "Our findings were remarkable, especially considering a report that detected the Spike protein using different technologies including Western-blot analysis after enriching CD9/CD81/CD63 EV subpopulations in COVID-19 patients." (PMID 39569406, 2024). "CD63, commonly used as an exosome marker, increased protein expression, and correlated to higher exosome levels in severely ill COVID-19 patients." (PMID 38262689, 2024). "The increase in CD62P and CD63 membrane expression on platelets co-cultured with the endothelium exposed to COVID-19 plasma appeared to be quite moderate." (PMID 37215546, 2023). "Plotting CD63 levels of healthy platelets activated by plasma from COVID-19 patients revealed a potential relationship between platelet activation capacity and future thrombosis." (PMID 35309299, 2022). "We examined which of these circulating inflammatory mediators correlated with the ability of COVID-19 plasma to induce CD63 expression on platelets from healthy donors." (PMID 35309299, 2022). "In line with the observation that CD63 modulates platelet spreading on immobilized fibrinogen, it has been demonstrated that platelets from COVID-19 patients exhibit greater adhesion and spreading on fibrinogen and collagen." (PMID 34977191, 2021). "Recent studies identified high CD63 messenger RNA levels as part of an immature proneutrophil/preneutrophil signature, which was found to be significantly enriched in COVID-19 patients." (PMID 34548411, 2021). "We observed a significant increase in CD63 and CD66b expression which was specific to the COVID-19 ARDS neutrophils." (PMID 33997298, 2021). "In this regard, we found a robust CD63 up-regulation on CD16dim neutrophils and a further increased expression in COVID-19 patients." (PMID 34548411, 2021).